CDKN1B (cyclin dependent kinase inhibitor 1B)
Diseases named in the same sentence as CDKN1B in open-access papers (continued):
Sharing a sentence is not in itself a finding about the gene and the disease.
acromegaly (17 papers, 2014 to 2026). Acromegaly is an acquired disorder related to excessive production of growth hormone (GH) and characterized by progressive somatic disfigurement (mainly involving the face and extremities) and systemic manifestations. "A germline heterozygous stop-gain mutation in the cyclin dependent-kinase inhibitor p27(Kip1), encoded by CDKN1B, was identified in the proband with acromegaly and HPT and in several other members of this kindred." (PMID 33716975, 2021). "However, without genetic studies on gene mutations (e.g., AIP, PRKAR1A, GPR101, GNAS, MEN1, CDKN1B, SDHx, MAX, it is difficult to assess whether OL-23/77 was affected by gigantism and acromegaly or just one of these diseases." (PMID 35498425, 2022). "Tumor expression of particular genes was found of prognostic/predictive value in acromegaly patients, These genes include basically CDH1 and SSTR2 but also CDKN1B SNAI2, FLNA, ARRB1, SNAI1 RORC ESRP1, and MKI67." (PMID 39497133, 2024). "Differences between transcriptomic groups were also observed in expression levels of proliferation-related genes CCND1, CDKN1B, and MKI67 and genes involved in cell signaling TGFB1 and STAT3 that all have a reported role in acromegaly patients’ outcome." (PMID 36497102, 2022). "Sixteen patients with acromegaly and PHP underwent rigorous genetic testing with DNA sequence analysis performed for genes including: MEN1, CDC73, CDKN1A, CDKN1B, CDKN2B, CDKN2C, and AIP, as well as MLPA to search for deletions or duplications in MEN1, CDC73, CDKN1B, and AIP genes." (PMID 32311048, 2020). "Four of the 15 different germline CDKN1B variations so far identified were detected in patients with F-MEN1, while the remaining were detected in patients with FIPA, FIHP, S-MEN1 or patients with sporadic PHPT or acromegaly." (PMID 29036195, 2017). "Therefore, in an acromegaly/gigantism patient with features of the MEN1 syndrome but without MEN1 mutations, screening for CDKN1B mutations is indicated." (PMID 28161730, 2017).
parathyroid adenomas (17 papers, 2015 to 2025). "Patients harbouring CDKN1B variants were included in the study because of atypical parathyroid adenomas, plus age under 45 years at diagnosis in case ID29." (PMID 37810884, 2023). "Two novel likely pathogenic CDKN1B variants were found in patients with atypical parathyroid adenomas." (PMID 37810884, 2023). "NGS of parathyroid adenoma, adrenal cortical adenoma, and pancreatic neuroendocrine tumor identified the same CDKN1B (c.179G > A, p.Trp60*) variant as was present in the germline." (PMID 35323929, 2022). "NGS of parathyroid adenoma identified the identical CDKN1B (c.475G > A, pAsp159Asn) variant as was present in the germline with no LOH." (PMID 35323929, 2022). "Here, we report a study on the effect of c.25A>C (pG9R) CDKN1B substitution, a germinal mutation identified in heterozygosity in a parathyroid adenoma seen as MEN‐related syndrome." (PMID 33316141, 2021). "Molecular genetic analysis of sporadic parathyroid adenomas demonstrating that CDKN1B mutation can be both somatic and clonal further supports the characterization of CDKN1B as a gene predisposing to the development of primary parathyroid tumors." (PMID 33716975, 2021). "In the primary parathyroid adenoma specimen of the patient with the CDKN1B heterozygous mutation (c." (PMID 33316141, 2021). "Loss-of-heterozygosity was detected in two of five parathyroid adenomas, supporting that CDKN1B acts as a tumor suppressor gene." (PMID 30990521, 2019). "Moreover, CDKN1B mutations have also been functionally linked to the development of parathyroid tumors, thereby solidifying the role of aberrant cell cycle regulation in the development of parathyroid adenomas." (PMID 33269427, 2021). "MEN4 can mimic MEN1, and CDKN1B mutations are implicated in the development of parathyroid adenomas as well." (PMID 38244045, 2024). "The positive P27 staining in the rim of normal tissue surrounding the parathyroid adenoma in our patient provides strong support for the occurrence of a second somatic hit at the CDKN1B locus." (PMID 25416039, 2015). "Moreover, mutational and/or epigenetic silencing of other genes predisposing for FIHP and MEN1-like syndromes have also been detected in small subsets of apparent sporadic parathyroid adenomas, including CDKN1A, CDKN1B, CDKN2A, CDKN2B, CDKN2C, and GCM2." (PMID 33269427, 2021). "Notably, somatic LOH at the CDKN1B locus is rarely observed in MEN4 parathyroid adenomas, although immunohistochemical staining of affected parathyroid tissue does not detect any tissutal expression of the p27Kip1 protein." (PMID 39519139, 2024).
leukemia (15 papers, 2013 to 2025). A malignant (clonal) hematologic disorder, involving hematopoietic stem cells and characterized by the presence of primitive or atypical myeloid or lymphoid cells in the bone marrow and the blood. "According to the literature, CDKN1B mutations have been previously reported in childhood leukemia and rarely in T-cell prolymphocytic leukemia as well as in adult T-cell leukemia." (PMID 25213837, 2014). "The gene of cyclin-dependent kinase inhibitor 1B (p27) is located with a high incidence translocation region of leukemic chromosomes, and its expression was of prognosis values in a variety of adult leukemia types." (PMID 30065619, 2018). "Inactivation of the cyclin-dependent kinase inhibitor 1B gene, located on the chromosome 12 CDKN1B (12p13.1), is response for uncontrolled cell proliferation and has been observed in leukaemias." (PMID 33467425, 2021).
neuroblastoma (15 papers, 2012 to 2024). Neuroblastoma (NB) is the most common solid, extracranial childhood tumor. "We propose that low CDKN1B levels seem to be involved in neuroblastoma initiation/progression and the T allele in promoter of CDKN1B is associated with low mRNA levels and confers the risk for neuroblastoma development." (PMID 28667701, 2017). "In the present study, we have analysed a total of 2412 neuroblastoma cases and 4911 controls and demonstrate that the SNP rs34330, located in the promoter of CDKN1B gene, is associated with neuroblastoma." (PMID 28667701, 2017). "Our study shows that a functional variant, associated with a reduced CDKN1B gene transcription, influences neuroblastoma susceptibility." (PMID 28667701, 2017). "To discover SNPs associated with neuroblastoma at the CDKN1B locus, we performed a genotype imputation on a discovery case series of 2101 neuroblastoma patients and 4202 genetically matched controls of European ancestry." (PMID 28667701, 2017). "Analysis of two publicly available gene expression array data of neuroblastoma showed that high CDKN1B expression is associated with better overall and event‐free survival and favourable stages." (PMID 28667701, 2017). "To verify a potential role of CDKN1B in neuroblastoma, we evaluated whether its expression is associated with clinical outcome of patients." (PMID 28667701, 2017). "We thus assess whether genetic variants of CDKN1B are associated with neuroblastoma." (PMID 28667701, 2017). "For example, overexpression of CDKN1B in mouse neuroblastoma cells was found to induce cell differentiation." (PMID 38356706, 2024). "Diverse lines of evidence from in vitro to clinical studies suggest that CDKN1B can play a role in neuroblastoma development and progression." (PMID 28667701, 2017). "We imputed all possible genotypes across CDKN1B locus on a discovery case series of 2101 neuroblastoma patients and 4202 genetically matched controls of European ancestry." (PMID 28667701, 2017). "There is evidence suggesting the CDKN1B, coding for the cycle inhibitor p27Kip1, is involved in neuroblastoma." (PMID 28667701, 2017). "Three independent sets of neuroblastoma tumours carrying ‐79TT genotype showed a tendency towards lower CDKN1B mRNA levels." (PMID 28667701, 2017). "Recent literature data suggest CDKN1B plays a role in neuroblastoma." (PMID 28667701, 2017).
multiple endocrine neoplasia type 4 (14 papers, 2015 to 2025). "Multiple endocrine neoplasia type 4 (MEN4) results from heterozygous inactivating mutations in the CDKN1B tumor suppressor gene." (PMID 39398337, 2024). "Multiple endocrine neoplasia type 4 (MEN4) is characterized by germline mutations in CDKN1B, located on chromosome 12p13.1." (PMID 38038882, 2024). "Interestingly, the P117S mutation in the cell cycle inhibitor CDKN1B has been associated with multiple endocrine neoplasia type IV (MEN4)." (PMID 41458559, 2025). "Interestingly, mutations of CDKN1B are also known as multiple endocrine neoplasia type 4 (MEN4)." (PMID 33732215, 2021). "Inactivating germline mutations of the CDKN1B gene encoding the nuclear cyclin-dependent kinase inhibitor P27kip1 protein have been reported in patients with multiple endocrine neoplasia type 4 (MEN4), a MEN1-like phenotype without MEN1 mutations." (PMID 25416039, 2015).
thyroid cancer (14 papers, 2009 to 2024). "Interestingly, the T allele of rs34330, which maps to the CDKN1B promoter region (‐79 C/T), has been reported to be associated with other tumours including breast 26, endometrial 27, lung 28 and thyroid cancer and with low gene expression of CDKN1B29." (PMID 28667701, 2017). "For example, miR-221 and miR-222 can facilitate cell proliferation by targeting CDKN1B (also known as p27Kip1) in thyroid cancer cells." (PMID 33066509, 2020). "The current research about the incidence, metastasis, and prognosis of thyroid cancer indicated that PIK3CA, PTEN, CDKN1B, TSHR, and EIF1AX were also involved, which should be considered in the multi-gene panel." (PMID 39600648, 2024). "In thyroid cancer, IGF1-mediated activation of Akt promotes FoxO1 export from the nucleus, inhibition of FoxO1-mediated transcriptional activation of target genes like CDKN1B (p27KIP1) cell cycle inhibitor, thus promoting cell proliferation." (PMID 33673232, 2021).
adenoma (13 papers, 2008 to 2026). A neoplasm arising from the epithelium. "USP8-mutated adenomas showed higher level of POMC, CDC25A, MAPK4 but lower level of CCND2, CDK6, CDKN1B than USP8-wild-type tumors." (PMID 38862897, 2024). "In contrast to adenoma, investigated target genes CDKN1B, PTPN13, RND3, SOX2 and ZEB2 were up-regulated in CRC N0, except ONECUT2 and TGFB2, which were down-regulated." (PMID 31623346, 2019). "All investigated and expressed target genes, CDKN1B, PTPN13, RND3, SOX2 and ZEB2, were down-regulated in adenoma compared to normal mucosa of CRC N0, except ONECUT2 and TGFB2, which were up-regulated." (PMID 31623346, 2019). "The majority of target genes (CDKN1B, PTPN13, RND3, SOX2 and ZEB2) were down-regulated in adenoma compared to normal mucosa." (PMID 31623346, 2019). "In contrast to miRNA, the only miRNAs target gene that was differentially expressed between adenomas and both CRC N0 and CRC N+ was CDKN1B (p < 0.001 and p = 0.001, respectively)." (PMID 31623346, 2019). "We also observed a statistically significant strong negative correlation between the expression of CDKN1B and miR-200a (rs = −0.648, p = 0.043) in adenomas." (PMID 31623346, 2019). "CDKN1B was expressed in all cases of adenoma, however, limited published data have reported that CDKN1B is not expressed in approx. 20% of adenomas and carcinomas and that its expression does not significantly change during the adenoma–carcinoma sequence/progression of CRC." (PMID 31623346, 2019).
hyperparathyroidism (12 papers, 2019 to 2025). Hyperfunction of the parathyroid glands resulting in the overproduction of parathyroid hormone. "While MEN1, MEN4, and hyperparathyroidism-jaw tumor syndrome involve inactivating pathogenic variants of tumor suppressor genes MEN1, CDKN1B, and CDC73, respectively, MEN2 is caused by activating mutations of RET proto-oncogene." (PMID 40277809, 2025). "Because part of the differential diagnosisincluded parathyroid carcinoma and hyperparathyroidism–jaw tumor syndrome,genetic testing for MEN1, CDC73,AP2S1, CASR, CDKN1B,GNA11 and RET was ordered and resultednegative." (PMID 39700332, 2024).
liver cancer (12 papers, 2012 to 2025). An epithelial or non-epithelial malignant neoplasm that arises from the liver. "We verified the expression levels of the representative gene pair PLOD2 /CDKN1B in 45 liver cancer samples, and combined with the OS and RFS of the corresponding patients, we found that PLOD2 /CDKN1B can better predict the prognosis of the patients." (PMID 34095224, 2021). "We found that PATZ1 modulates liver cancer cell proliferation by regulating CDKN1B, a key cyclin-dependent kinase inhibitor." (PMID 33598459, 2021). "In summary, we have demonstrated that PATZ1 inhibits cell proliferation by promoting CDKN1B expression, thereby indicating that PATZ1 functions as a tumor suppressor in liver cancer." (PMID 33598459, 2021). "hsa-miR-24-3p, but not hsa-miR-21-5p, also induces growth in human liver cancer cells (HEPG2) and has been reported to promote the growth of cancer cells through inhibition of the cyclin-dependent kinase inhibitor 1B (CDKN1B/p27kip1)." (PMID 35132877, 2021).
bladder cancer (11 papers, 2001 to 2025). "In bladder cancer cells ATG7 is reported to indirectly repress the expression of FOXO1, which controls the expression of CDKN1B gene encoding for a second CDK inhibitor p27." (PMID 34082793, 2021). "Five of the 26 SMGs had not been reported as SMGs in bladder cancer in previous studies: CDKN1B (1.2%), ITK (1.8%), PRDM2 (3.1%), FOXA1 (2.7%), and BAP1 (1.8%)." (PMID 36495164, 2023). "Another study from 2015 reported that cytoplasmic p27, also known as cyclin dependent kinase inhibitor 1B (CDKN1B), can promote epithelial to mesenchymal transition (EMT) and metastasis via the STAT3-TWIST1 pathway in human mammary epithelial cells, breast cancer, and bladder cancer." (PMID 41148789, 2025).
head and neck cancer (11 papers, 2006 to 2024). A primary or metastatic malignant neoplasm affecting the head and neck. "CAFs derived exosomes miR-196a make advanced head and neck cancer resistant to CDDP by targeting cyclindependent kinase inhibitor 1B (CDKN1B) and inhibitor of growth family (ING5)." (PMID 37666813, 2023). "In head and neck cancer, miRNA-196a has been shown to promote cisplatin resistance by targeting (cyclin-dependent kinase inhibitor 1B (CDKN1B)." (PMID 35331235, 2022). "Additionally, CAF-derived exosomal miR-196a was found to confer cisplatin resistance in head and neck cancer (HNC) by targeting cyclin-dependent kinase inhibitor 1B (CDKN1B) and inhibitor of growth 5 (ING5)." (PMID 33869017, 2021). "For example, in head and neck cancer cells, CAF-Exo miR-196a reduced the expression of CDKN1B (Cyclin Dependent Kinase Inhibitor 1B), a gene critical for the change from the G1 to the S phases of the cell cycle." (PMID 39187523, 2024). "Interestingly, we found that the expression of CDKN1B (p27), a cell-cycle and DNA damage regulator, was significantly decreased in our cohort of patients with malnutrition and was the most reliable marker for differentiating malnutrition in head and neck cancer patients." (PMID 35158762, 2022). "CAFs secreted exosomal miR-196a to cancer cells, targeting CDKN1B and ING5 and mediating cisplatin resistance in head and neck cancer." (PMID 36319622, 2022).
parathyroid tumors (11 papers, 2015 to 2024). "Thus, there is some evidence that cyclin-dependent kinase inhibitors (CDKI) gene mutations can lead to parathyroid tumor development, particularly the mutations in CDKN1B/p27 gene." (PMID 35628190, 2022). "Parathyroid neoplasms can also be associated with multiple endocrine neoplasia (MEN) syndromes MEN1, MEN2A, and MEN4, caused by mutations in the genes MEN-1, RET, and CDKN1B, respectively." (PMID 36900197, 2023). "CDKN1B, which encodes p27, is the most extensively studied member of the CDKN1 family with respect to parathyroid tumors." (PMID 33778063, 2021). "However, germline mutations in Cdkn1b cause a MEN (multiple endocrine neoplasia) syndrome in humans and rats characterized by pituitary and parathyroid tumors." (PMID 30893315, 2019). "The same authors found significant overexpression of CDKN1B mRNA compared with CDKN1B-non-mutated parathyroid tumors and normal parathyroid." (PMID 25416039, 2015).
primary hyperparathyroidism (11 papers, 2015 to 2025). "General information: This rare syndrome is caused by germline mutations of the CDKN1B (cyclin-dependent kinase inhibitor 1B) tumor-suppressor gene and is characterized by the association of primary hyperparathyroidism and pituitary, renal, and adrenal tumors." (PMID 39194755, 2024). "To date, only a small number of families have been identified with germline mutations in CDKN1B and of those cohorts, patients with primary hyperparathyroidism have almost exclusively been women who present in middle age." (PMID 26257968, 2015). "In this study, we report a large family with several individuals characterized by development of primary hyperparathyroidism and other endocrine tumors, and these features of MEN segregated with a pathogenic variant in CDKN1B over two generations." (PMID 30990521, 2019). "We report a case of primary hyperparathyroidism presenting with renal stones at age 15 associated with a novel germline heterozygous missense mutation in CDKN1B." (PMID 26257968, 2015). "In our case, we have identified early onset primary hyperparathyroidism, with its associated complications (renal stones) present at age 15 associated with a germline CDKN1B variant but no other features of MEN4." (PMID 26257968, 2015).
atherosclerosis (10 papers, 2010 to 2025). A disease characterized by the build-up of fatty material and calcium deposition in the arterial wall resulting in partial or complete occlusion of the arterial lumen. "Increased expression of CDKN1B is associated with structural and functional changes in the kidneys in diabetic nephropathy, decreased pancreatic β-cell proliferation and serum insulin levels, as well as decreased macrophage proliferation and inflammation in atherosclerosis." (PMID 39273245, 2024). "Mounting evidence suggested that CDKN1B is a key regulator of cell cycle progression, which was recognized as an important senescence marker in aging-related diseases such as osteoporosis, atherosclerosis and Alzheimer’s disease." (PMID 37055817, 2023).
esophageal cancer (9 papers, 2017 to 2023). A primary or metastatic malignant neoplasm involving the esophagus. "Overexpression of CDKN1B gene in specific cancer cells prevents DNA replication and tumorigenesis, whereas its deficiency plays an inhibitory role in human cancers and decreases the chance for developing breast, prostate, colon, lung, and esophagus cancers." (PMID 33324444, 2020). "Additionally, restoration of pristimerin significantly inhibited cell proliferation in esophageal cancer cell lines by acting on CDKN1B." (PMID 31218209, 2019). "Here, we showed that knockdown of CDKN1B can inhibit esophageal cancer cell growth." (PMID 31218209, 2019).